HMGB1 (high mobility group box 1)
Diseases named in the same sentence as HMGB1 in open-access papers (continued):
Sharing a sentence is not in itself a finding about the gene and the disease.
diabetic nephropathy (28 papers, 2012 to 2025). "This action reduces HMGB1 (high mobility group box 1) levels, reverses the downregulation of autophagy, and alleviates podocyte injury and diabetic nephropathy caused by HG." (PMID 40851276, 2025). "This study presents a robust immunoinformatics-to-validation pipeline for identifying serologically detectable B-cell epitopes from HMGB1, S100A8, and S100A9—three key DAMP proteins implicated in diabetic nephropathy." (PMID 41367913, 2025). "Clinical approaches targeting TLRs in diabetic nephropathy include montelukast, which reduces renal inflammation by suppressing HMGB1/TLR4/NF-κB signaling." (PMID 40584714, 2025). "The SGLT2 inhibitor dapagliflozin can reduce HMGB1 levels and improve renal function in diabetic nephropathy." (PMID 40004134, 2025). "In the context of diabetic nephropathy, HMGB1 has been shown to play a role in the development and progression of renal injury." (PMID 40004134, 2025). "Previous studies have reported the potential role of HMGB1-induced RAGE activation-mediated TGF-β secretion in PTECs leading to fibrosis-like pathology in various renal diseases such as diabetic nephropathy." (PMID 38201260, 2023). "Blocking the interaction between HMGB1 and its receptors has been proved to be effective in preventing the development of diabetic nephropathy (DN)." (PMID 33565572, 2021). "Given the interest matured towards HMGB1 and its relationship with DM pathogenesis, several studies have evaluated its role in development and progression of diabetic nephropathy, retinopathy and neuropathy." (PMID 31835864, 2019). "Previous researches have demonstrated the pathological roles for HMGB1-RAGE interaction involved in diabetic nephropathy and diabetic retinopathy." (PMID 31929852, 2019). "We prospectively followed 165 individuals with diabetic nephropathy and 168 individuals with persistent normoalbuminuria who were free of CVD at study entry and in whom levels of HMGB1 and other cardiovascular risk factors were measured at baseline." (PMID 22752054, 2012). "In the present study, we explored whether HMGB1 regulates ferroptosis dependent on Nrf2 signaling in the context of diabetic kidney disease." (PMID 33565572, 2021). "During early stages of diabetic nephropathy, TLR4/NF-κB signaling is activated via upregulation of HMGB1, in turn promoting cytokine release, inflammation, and proteinuria." (PMID 31441362, 2019). "Recently, it has been identified as a TLR4 endogenous ligand in diabetic conditions, HMGB1 and TLR4 level was increased in kidney tubular cells in diabetic nephropathy biopsies." (PMID 28542370, 2017). "We and others have also shown evidence for TGFβ induced activation of the innate immunity pathway in diabetic nephropathy, in particular Toll like receptor 2 (TLR2) and its endogenous ligand High Mobility Group Box 1 (HMGB1)." (PMID 25369239, 2014). "Moreover, extracellular HMGB1 is involved in streptozotocin‐induced diabetic nephropathy (DN) via its activation of TLR2, TLR4 and RAGE, while blockade of HMGB1 signalling attenuates streptozotocin‐induced DN." (PMID 35706377, 2022). "In particular, Lin and coworkers demonstrated that in renal tubules of subjects with diabetic nephropathy, there is increased expression of TLR-4 and HMGB1, but not of TLR-2." (PMID 31835864, 2019). "Similarly, in vivo data showed an increase in tubular TLR2, HMGB1, and fibronectin expression, with no increase in TLR4 expression, suggesting that the HMGB1-TLR2-NF-κB pathway might play a dominant role in mediating inflammation in diabetic nephropathy in the long term." (PMID 40584714, 2025).
inflammatory bowel disease (28 papers, 2013 to 2025). A spectrum of small and large bowel inflammatory diseases of unknown etiology. "Whether the risks associated with anti-HMGB1 treatment in inflammatory bowel disease will outweigh the benefits needs to be tested in future studies." (PMID 33193406, 2020). "High levels of secreted HMGB1 are observed in the faeces of inflammatory bowel disease (IBD) patients, indicating its role in IBD pathophysiology and potential as a non-invasive IBD biomarker." (PMID 36551259, 2022). "Fecal HMGB1 was found to be a marker of intestinal inflammation, as it was not only significantly increased in the stool of Inflammatory Bowel Disease (IBD) patients, compared with controls, but also indicative of the course of the disease." (PMID 32796569, 2020). "HMGB1 is abundantly secreted and/or released in the intestinal tissues of human inflammatory bowel diseases patients, and fecal HMGB1 was recognized as the marker for intestinal inflammation." (PMID 29491864, 2018). "HMGB1 is secreted by human inflamed intestinal tissues and is abundantly found in the stools of pediatric patients with inflammatory bowel diseases (IBDs), so that HMGB1 has been proposed as a novel marker of intestinal mucosal inflammation." (PMID 29682486, 2017). "For all these reasons, HMGB1 is actually considered a potent inflammatory mediator and has been implicated in several inflammatory and auto-immune disorders, such as sepsis, rheumatoid arthritis, lupus erythematosus, myositis, diabetes and, ultimately, inflammatory bowel disease (IBD)." (PMID 23840500, 2013). "Extracellular High-mobility group box 1 (HMGB1) contributes to the pathogenesis of inflammatory disorders, including inflammatory bowel diseases (IBD)." (PMID 37108260, 2023). "Intestinal HMGB1 was described as an inflammatory bowel disease (IBD) marker in children and a marker of the severity of enteric infections in GN piglets." (PMID 36768650, 2023). "Many recent studies have indicated that HMGB1 protein is involved in the development of inflammatory bowel disease (IBD)." (PMID 33182652, 2020). "High mobility group box 1 protein (HMGB1) is involved in the pathogenesis of inflammatory bowel disease (IBD)." (PMID 33182652, 2020). "Inflammasome-dependent mediators such as IL-1β, IL-18, and HMGB1 have been identified as potent promoters of intestinal pathology, which suggests that targeting these mediators may represent a useful therapeutic approach in inflammatory bowel disease (IBD)." (PMID 26355424, 2015). "Of note, these findings coincide with the reported HMGB1 downregulation by linagliptin in chondrogenic ATDC5 cells and an animal model of inflammatory bowel disease." (PMID 35890148, 2022). "Furthermore, clinical studies have revealed that HMGB1 is relevant in colonic inflammation and inflammatory bowel disease (IBD)‐like phenotypes with NAFLD." (PMID 35706377, 2022). "We have previously shown in patients with inflammatory bowel disease (IBD) that fecal HMGB1 is a robust non-invasive biomarker of mucosal inflammation and healing, suggesting its potential role in the diagnostic approach and monitoring intestinal inflammation in children." (PMID 34178888, 2021). "Fetuin-A is believed to play a protective role in inflammatory bowel disease (IBD) by acting as an endogenous inhibitor of meprin-α, which plays an essential role in IBD pathogenesis by activating inflammatory cytokines and protecting against intestinal inflammation by inhibiting HMGB1 release." (PMID 34680053, 2021). "Furthermore, in the context of inflammatory bowel disease (IBD), enhanced serum levels of HMGB1 is accompanied by spontaneous IL-8 production by B-cells via interaction with TLR2 and CD36." (PMID 23519706, 2013).
lung adenocarcinoma (28 papers, 2014 to 2025). A carcinoma that arises from the lung and is characterized by the presence of malignant glandular epithelial cells. "On the other hand, the extracellular release of HMGB1 accompanied apoptotic and necroptotic cell death in Cisplatin-susceptible lung adenocarcinoma cell lines." (PMID 38001683, 2023). "Cisplatin-susceptible lung adenocarcinoma cell lines died by apoptosis or necrosis and released HMGB1." (PMID 34966671, 2021). "Autophagy-associated HMGB1 has been revealed to protect various cancer cells, such as osteosarcoma, lung adenocarcinoma, neuroblastoma and ovarian cancer, from many chemotherapeutics, including DOX, cisplatin and etoposide." (PMID 32322202, 2020). "In lung adenocarcinoma, high levels of HMGB1 correlated positively with tumor staging and were associated with poor survival." (PMID 29472602, 2018). "In this study, we found that a high expression of HMGB1 in lung adenocarcinoma tissues was associated with the expression of cancer EMT markers." (PMID 28727734, 2017). "In conclusion, HMGB1 may be an effective biomarker associated with increased overall survival of lung adenocarcinoma patients." (PMID 34966671, 2021). "This study indicated polymorphisms in HMGB1 may be a novel biomarker for female lung adenocarcinoma risk." (PMID 29617336, 2018). "In human lung adenocarcinoma, HMGB1-mediated autophagy via the mitogen-activated protein kinase (MEK)/extracellular signal-regulated kinase (ERK) signalling pathway enhances docetaxel resistance." (PMID 41151762, 2025). "In lung adenocarcinoma, cisplatin-persistent cells accumulate nuclear HMGB1 and upregulate RAGE, indicating a coordination between extracellular immunomodulation and intracellular DNA damage repair signaling." (PMID 41465435, 2025). "High mobility group box-1 (HMGB-1) is highly expressed in lung adenocarcinoma exosomes and promotes glycolysis in the tumor macrophages by upregulating PD-L1 expression." (PMID 36588730, 2022). "We used the databases of the TCGA-LUSC and TCGA-LUAD projects and analyzed the association between high HMGB1 expression and OS and poor DFS in lung adenocarcinoma." (PMID 36230798, 2022). "This work was focused on the role of HMGB1 in lung adenocarcinoma and its relevance as a biomarker of response to therapy and OS." (PMID 34966671, 2021). "Overall, these results suggest that the HMGB1–RAGE axis plays an important role in CDDP resistance following treatment of lung adenocarcinoma cell lines." (PMID 34966671, 2021). "We quantified HMGB-1 as a key DAMP release during the follow-up of lung adenocarcinoma patients to evaluate its potential as a biomarker." (PMID 33167343, 2020). "In order to explore the function of HMGB1, stable and sustained overexpression of HMGB1 on lung adenocarcinoma cell lines is required." (PMID 28727734, 2017). "In terms of prognostic features, a survival analysis from KM-Plotter tool revealed that the high HMGB1 expression group exhibited poorer survival in lung adenocarcinoma (ADC) and overall NSCLC patients." (PMID 26840258, 2016). "The TCGA data (Lung Adenocarcinoma, Provisional) was analyzed by cBioPortal, and it showed that HMGB1 was over-expressed in 26% of cases." (PMID 26840258, 2016). "Lung adenocarcinoma (LAD) cells were transfected with pcDNA3.1-HMGB1 or HMGB1 shRNA, followed by docetaxel treatment." (PMID 24996221, 2014). "However, lung adenocarcinoma samples showed a substantially greater HMGB1 concentration than lung squamous cell carcinoma." (PMID 37518006, 2023). "In this study, eight cytokines and HMGB1 were quantified in patients with lung adenocarcinoma." (PMID 33167343, 2020). "HMGB1-mediated autophagy through the mitogen-activated protein kinase (MEK)/extracellular signal-regulated kinase (ERK) signaling pathway promotes docetaxel resistance in human lung adenocarcinoma." (PMID 32322202, 2020).
lung adenocarcinoma (continued). "Furthermore, the expression of HMGB1 in lung adenocarcinoma tissue was reported to be significantly higher than that in lung squamous cell carcinoma tissue, and it was associated with patient survival." (PMID 28727734, 2017). "Of these, a 21-gene signature in the HMGB1/RAGE signalling pathway and a 31-gene signature in the clathrin-coated vesicle cycle pathway were significantly associated with prognosis of lung adenocarcinoma across all four datasets (all p-values < 0.05, log-rank test)." (PMID 26042604, 2015). "Moreover, at the post-transcriptional level, circular RNA G6PC3 was found to promote lung adenocarcinoma progression by physically binding to both HMGB1 and Beclin 1, thereby stabilizing their interaction and enhancing the formation of the pro-autophagic HMGB1/Beclin 1 complex." (PMID 41465435, 2025). "Finally, changes in plasma HMGB1 from a cohort of lung adenocarcinoma patients without EGFR mutation and treated with cisplatin-based therapy were analyzed." (PMID 34966671, 2021). "Finally, changes in plasma HMGB1 levels in a cohort of lung adenocarcinoma patients without EGFR mutations and treated with CDDP-based chemotherapy were determined." (PMID 34966671, 2021). "In our study, no change in HMGB-1 concentrations during treatment could be associated with advanced stages of lung adenocarcinoma." (PMID 33167343, 2020). "There was a downregulation of most of necroptosis-related genes in lung adenocarcinoma (LUAD) versus lung tissues but an increase in PGAM5, HMGB1, TRAF2, EZH2 levels." (PMID 37965055, 2023). "HMGB1 expression was higher in lung squamous cell carcinoma (LUSC) and was lower in lung adenocarcinoma (LUAD) tissue than in normal lung tissue." (PMID 35923467, 2022). "In addition, the expressions of both HMGB1 and DRP1 revealed positive correlations in lung adenocarcinoma (Pearson correlation coefficient = 0.54, p = 5.87 × 10−11; Kendall tau = 0.506; p = 3.34 × 10−17)." (PMID 33807275, 2021). "Our results noted that HMGB1 should mostly affect the survival and prognosis of lung adenocarcinoma; however, the molecular mechanisms at play were not so clear." (PMID 26840258, 2016). "HMGB1 was not expressed in the supernatants of infected primary HCF, the human lung adenocarcinoma cell line A549, or the human embryonic kidney cell line HEK293." (PMID 40367285, 2025).
periodontitis (27 papers, 2014 to 2026). An acute or chronic inflammatory process that affects the tissues that surround and support the teeth. "AGEs receptors (RAGE) in tissues and plasma of diabetic patients bound to HMGB1 are key in the association between periodontitis and diabetes." (PMID 37396128, 2023). "Blockade of HMGB1 by soluble RAGE (sRAGE) suppressed periodontitis-associated bone loss in diabetic mice, and serum levels of sRAGE and cleaved RAGE were significantly lower in periodontitis patients." (PMID 32760399, 2020). "In JIA, which is characterized by chronic inflammation and periodontitis, it was indicated that the presence of various functional HMGB1 redox isoforms confirms the complexity of their pathogenic role during chronic inflammation." (PMID 32760399, 2020). "The increased expression of CXCL1 in periodontitis may be caused by other factors such as high mobility group box 1 (HMGB1)." (PMID 35806156, 2022). "In conclusion, this study demonstrates that HMGB1 may be associated with the onset and progression of periodontitis, suggesting that further studies should investigate the potential role of HMGB1 on periodontal tissue destruction." (PMID 24692854, 2014). "Metformin also alleviates HMGB1-mediated oxidative stress through the mTOR pathway in experimental periodontitis." (PMID 40385486, 2025). "Future investigations should delve into the involvement of HO-1 in the inter-regulation of critical pathways, including MAPK, NF-κB and PI3K/Akt, as well as the potential of HMGB1 as a significant target for the regulation of periodontitis treatment by HO-1." (PMID 39430558, 2024). "Other examples of DAMPs found to be elevated in periodontitis are high-mobility group box-1 (HMGB1) and HMGN2, both transcription factors, and IL1." (PMID 39061769, 2024). "In diabetic mice with periodontitis, glycyrrhizic acid can suppress the production of HMGB1 and RAGE mRNA in the gingiva and serum and lessen the inflammatory response of the periodontal tissue." (PMID 37396128, 2023). "In vivo test using a rat periodontitis model treated with glycyrrhizin revealed the downregulation of HMGB1, IL-6, and IL-1β in the gingival crevicular fluid and periodontal tissue." (PMID 37396128, 2023). "For instance, anti-HMGB1 neutralizing antibody inhibited periodontal inflammation and bone resorption in an animal periodontitis model." (PMID 35251521, 2022). "Consistently, we will recapitulate below the current observations on the involvement of complement (and HMGB1 in the next section) in severe periodontitis." (PMID 35572583, 2022). "Anti-HMGB1 antibodies were shown to attenuate periodontal inflammation and bone resorption in a murine periodontitis model." (PMID 35572583, 2022). "Administration of an anti-HMGB1 neutralizing antibody in an experimental periodontitis model attenuated alveolar bone resorption and inflammatory cytokines." (PMID 34445604, 2021). "For instance, it has been shown that the inflammatory response induced by periodontal infection stimulates the secretion of HMGB1, while inhibition of HMGB1 attenuates the levels of inflammatory cytokines in the mouse periodontitis model." (PMID 34366853, 2021). "In our study, administration of anti-HMGB1 antibody in a murine periodontitis model inhibited myeloperoxidase (MPO) activity, neutrophil migration, and bone resorption in a dose-dependent manner." (PMID 32760399, 2020). "Secretion of HMGB1 around periodontal tissue is considered to promote pro-inflammatory cytokine production and prolong periodontitis." (PMID 32760399, 2020). "It was revealed that HMGB1 is involved in the aggravation of periodontitis by HMGB1 blockade analysis." (PMID 32760399, 2020). "Infection promotes HMGB1 secretion from periodontal tissue, and the secreted HMGB1 is involved in the lingering or aggravation of periodontitis." (PMID 32760399, 2020).